PCSK9 (proprotein convertase subtilisin/kexin type 9)
Diseases named in the same sentence as PCSK9 in open-access papers (continued):
Sharing a sentence is not in itself a finding about the gene and the disease.
hepatocellular carcinoma (71 papers, 2007 to 2025). A malignant tumor that arises from hepatocytes. "In hepatocellular carcinoma, PCSK9 enhances M2 polarization of tumor-associated macrophages (TAMs); M2 macrophages contribute to cancer progression." (PMID 36588164, 2023). "In the HepG2 hepatocellular carcinoma cell line, which frequently serves as a hepatocyte model, leptin increased the expression of PCSK9, causing reduced LDL-R levels and impaired LDL uptake." (PMID 35162992, 2022). "PCSK9, proprotein convertase subtilisin/kexin type 9, is involved in cholesterol and fatty acid metabolism, and has been linked to various cancers, including hepatocellular carcinoma." (PMID 36503519, 2022). "Elevated PCSK9 levels are linked to the development of hepatic fat accumulation and even to the occurrence of human hepatocellular carcinoma (HCC)." (PMID 30650126, 2019). "Overexpression of PCSK9 has been observed in several cancer types indicating that PCSK9 holds promise as a diagnostic and prognostic biomarker, such as colorectal cancer, hepatocellular carcinoma, and gastric cancer." (PMID 39282119, 2024). "In addition to increasing LDL plasma levels, PCSK9 gain-of-function pathogenic variants have been found to increase circulating Lp(a) in FH patients, potentially by interfering with Lp(a) endocytosis, as shown in a human hepatocellular carcinoma model." (PMID 30050433, 2018). "The study indicates that abnormal overexpression of PCSK9 enhances cell proliferation and confers resistance to sorafenib in hepatocellular carcinoma by facilitating AKT-S473 phosphorylation." (PMID 40066091, 2025). "The mitogenic effects of PCSK9 have been reported through inhibiting tumor cell apoptosis in hepatocellular carcinoma." (PMID 40362754, 2025). "In hepatocellular carcinoma, PCSK9 was found to promote cell growth by inhibiting cell apoptosis via the involvement of the Bax/Bcl-2/Caspase-9/Caspase-3 pathway." (PMID 38611089, 2024). "This Ab exhibited 100% inhibition of PCSK9 in hepatocellular carcinoma models at a specific concentration (1.5 μM)." (PMID 38961200, 2024). "Further, we verified its biological activity using the human hepatoma cells G2 model, where the B11-H2-Fc exhibited almost 100% efficiency in PCSK9 inhibition at only 0.75 μM." (PMID 38961200, 2024). "Overexpression of PCSK9 was found in different cancer types, including colorectal cancer, breast cancer, lymphoblastic leukaemia, hepatocellular carcinoma and gastric cancer." (PMID 37765005, 2023). "For instance, PCSK9-/-mice had more severe fibrosing steatohepatitis and were more prone to hepatocellular carcinoma." (PMID 37350960, 2023). "There are various preclinical studies based on tumour tissue or mouse models that report the direct effects of PCSK9 or PCSK9 inhibitors on multiple types of cancer, including hepatocellular carcinoma, lung carcinoma, colorectal cancer, and breast cancer." (PMID 36595504, 2023). "miR-552-3p was reported to regulate PCSK9 levels in the human hepatocellular carcinoma cell line (HepG2)." (PMID 36980904, 2023). "On the other hand, in the case of hepatocellular carcinoma, in vivo and in vitro studies proved that PCSK9 has a protective influence against cancer growth and spread." (PMID 37765005, 2023). "The activation of this pathway in HepG2 cells is related to lipid metabolism, which also strongly influences the proliferation, migration and invasion of hepatoma cells and is regulated by PCSK9 and SREBP2." (PMID 35836300, 2022). "We assessed the effect of PCSK9 inhibition using the three hepatoma cell lines Huh6, Huh7 and HepG2 and validated the results using the zebrafish in vivo model." (PMID 36611859, 2022). "More recently, we inhibited PCSK9 expression in three hepatoma (HCC and HB) cell lines, Huh6, Huh7 and HepG2." (PMID 36552895, 2022). "The authors found that PCSK9 suppressed apoptosis in cultured hepatoma-derived cell lines through the Bax/Bcl-2/Caspase9/3 pathway." (PMID 34782856, 2021).
hepatocellular carcinoma (continued). "Conversely, gain-of-function mutant PCSK9 increases apoB100 secretion in a rat hepatoma-derived cell line, McArdle-7777 cells." (PMID 34782856, 2021). "Hepatic PCSK9 protein expression was found increased in the cirrhotic liver, and hepatocellular carcinoma adjacent tissues were used in this analysis." (PMID 33920491, 2021). "PCSK9 expression is high in various cancers, such as hepatocellular carcinoma, gastricadenocarcinoma and prostate cancer cell lines." (PMID 34782856, 2021). "Liraglutide, a once-daily glucagon-like peptide-1 (GLP-1) agonist, was found to suppress PCSK9 expression via a hepatocyte nuclear factor 1 alpha (HNF1α)-dependent mechanism in the human hepatoma cell line, HepG2." (PMID 31706300, 2019). "It should also be noted that even though insulin induced PCSK9 expression in rat/mouse hepatoma cells and primary hepatocytes, it exhibited either neutral or inhibitory effect on serum PCSK9 in human subjects." (PMID 30386595, 2018). "We found, in three different hepatocyte culture models (Huh7 hepatoma cells, primary human hepatocytes, and primary mouse hepatocytes), that PCSK9 promotes Lp(a) internalization." (PMID 28750079, 2017). "Insulin is reported to increase PCSK9 expression in hepatoma cells and primary hepatocytes, while another study found that insulin decreases PCSK9 expression and secretion from human cell lines." (PMID 28439730, 2017). "We found that PCSK9 decreased Lp(a) and/or apo(a) internalization by Huh7 human hepatoma cells and by primary mouse and human hepatocytes." (PMID 28750079, 2017). "Concomitant to LDL-R expression downregulation, cell-cultured HCV infection was impeded in a dose-dependent manner by addition of soluble PCSK9 to hepatoma cells, while cells stably expressing PCSK9 at their surface became resistant to HCV infection." (PMID 24278733, 2012). "In vitro, LDL-R expression was downregulated in hepatoma cells transiently expressing PCSK9, and, in vivo, mice knocked out for Pcsk9 displayed a drastic reduction in their liver expression level of LDL-R." (PMID 24278733, 2012). "The ability of the catalytically inactive PCSK9 to bind and degrade LDLRs when added to culture medium of human hepatoma HepG2 cells at physiological concentrations was similar to that seen using wild-type protein." (PMID 17537735, 2007). "PCSK9‐mediated LDL was positively associated with colon cancer (OR = 1.33, 95% CI: 1.10–1.16, p < 0.01) and negatively associated with rectal cancer (OR = 0.63, 95% CI: 0.53–0.76, p < 0.01) and hepatocellular carcinoma (OR = 0.63, 95% CI: 0.40–0.97, p = 0.04)." (PMID 40443776, 2025). "PCSK9 displays oncogenic actions in cancer, including gastric cancer, esophageal cancer, prostate cancer, breast cancer, ovarian cancer, lung cancer, hepatocellular carcinoma, and melanoma." (PMID 36588164, 2023). "However, some researchers have also found that interference with PCSK9 results in abnormal lipid metabolism, high lipid peroxidation and the ferroptosis of hepatocellular carcinoma cells." (PMID 37055467, 2023). "In hepatocellular carcinoma, PCSK9 has decreased expression compared to adjacent liver tissue." (PMID 36503519, 2022).
hepatocellular carcinoma (continued). "This article is to study the role of PCSK9 in the progression of hepatocellular carcinoma (HCC)." (PMID 33789749, 2021). "However, differently from statin, which induces PCSK9 expression, MK7 was shown to suppress PCSK9 synthesis and secretion by hepatoma cells." (PMID 32429343, 2020). "Based on microarray analyzes of hepatocellular carcinoma (HCC) cells, decreased expression of PCSK9 was found." (PMID 35323699, 2022). "Consequently, the inhibition of PCSK9 palmitoylation amplifies the anticancer efficacy of sorafenib in hepatocellular carcinoma (HCC)." (PMID 40066091, 2025). "Insulin increases LDL-R activity in human hepatoma cells whereas it increases the PCSK9 and LDL-R degradation in hepatoma cells and primary hepatocytes." (PMID 35586340, 2022). "In some cells, such as human hepatoma cells (Huh7 and HepG2) or human embryonic kidney cells (HEK293), PCSK9 significantly decreases the levels of LDLRs." (PMID 36552895, 2022). "One study reported PCSK9 attenuation in Human Umbilical Vein Endothelial Cells (HUVEC), two in Human Hepatocytes (Huh 7), twenty-seven in Human hepatoma (HepG2), and one in JLM3 (hepatocellular carcinoma cells)." (PMID 36232177, 2022). "In vitro studies in human hepatoma-derived cell lines (HepG2 and Huh7 cells) showed that BBR decrease PCSK9 mRNA and protein levels in a time- and dose-dependent manner." (PMID 22998978, 2012). "Similarly, in hepatocellular carcinoma (HCC), PCSK9 palmitoylation at Cys600 by ZDHHC16 enhances PTEN degradation, activating AKT-S473 phosphorylation and conferring sorafenib resistance." (PMID 40977744, 2025). "Taken together, the absence of ANGPTL3 determined lipid accumulation in human hepatoma cell line Huh7, by promoting the de novo lipogenesis independently from PCSK9, and without determining an increase in the secretion of apoB-containing lipoproteins." (PMID 38612519, 2024). "However, the precise role of PCSK9 and its relationship to the development of hepatocellular carcinoma (HCC) remain largely unknown." (PMID 33893729, 2021). "To date, current cellular models that are available to decipher PCSK9 functions are limited to heterologous cell lines or hepatoma cells with forced PCSK9 expression that are not suitable to clearly describe the intracellular action of PCSK9." (PMID 26586530, 2016). "A growing amount of evidence has manifested that PCSK9 show a promising advantage to cancer progression as well as poor clinical prognosis in several malignant tumors, such as melanoma, non-small cell lung cancer (NSCLC), breast cancer, and hepatocellular carcinoma(HCC)." (PMID 33489919, 2020). "However, this may not be representative for all human hepatocellular carcinoma cell lines as AnxA2 depletion in HepG2 cells, which express approximately 5-fold less AnxA2 mRNA compared to HuH7, did not alter PCSK9 or LDL-R protein expression." (PMID 28456096, 2017).
hepatocellular carcinoma (continued). "The correct folding of the C-terminal domain is crucial for PCSK9 function but catalytic activity is not required for PCSK9 to bind and degrade LDL-R in cultured human hepatoma cells." (PMID 17971861, 2007).
Insulin resistance (63 papers, 2013 to 2025). Increased resistance towards insulin, that is, diminished effectiveness of insulin in reducing blood glucose levels. "Instead, PCSK9 concentrations were more closely associated with metabolic disturbances, particularly excess body weight and insulin resistance." (PMID 41516208, 2025). "A study investigated the association of depression with insulin resistance, especially in obese patients and PCSK9 levels, and the cardiovascular outcome." (PMID 35911274, 2022). "Nevertheless, PCSK9 has been epidemiologically shown to mediate 11% of the association between depression and insulin resistance in a cohort of 389 obese patients." (PMID 36527064, 2022). "Some studies show that higher PCSK9 levels are associated with higher fasting blood glucose and plasma insulin and insulin resistance." (PMID 35024053, 2021). "In accordance with the previous findings, in our female population circulating PCSK9 is positively associated with fasting glucose and insulin resistance, which involved in the initiation and progression of cardiometabolic disease." (PMID 34041285, 2021). "In the context of CV prediction, PCSK9 concentrations, increased by insulin-resistance, are also associated with a raised susceptibility to MI, as assessed by genome association studies, although data from epidemiological studies are discordant." (PMID 33143700, 2020). "Recent studies have shown that circulating PCSK9 is associated with glucose homeostasis and insulin resistance." (PMID 33302966, 2020). "This study indicates a possible mechanism linking depression and insulin resistance, a well-known CV risk factor, providing evidence for a significant role of PCSK9." (PMID 33143700, 2020). "Insulin resistance, a condition found in PCSK9−/− mice, is linked with an impaired expression of natriuretic peptides (NPs) receptors in human VAT." (PMID 30634533, 2019). "We show here that PCSK9 was only positively associated with both whole-body and hepatic insulin resistance in healthy volunteers (including OffT2D) when they fed a short-term HFruc diet, but not under basal conditions." (PMID 23298392, 2013). "Upon this diet, PCSK9 is associated with insulin resistance, hepatic steatosis and plasma triglycerides." (PMID 23298392, 2013). "Circulating PCSK9 levels were associated with both whole-body, hepatic insulin resistance, liver steatosis and VLDL-TG." (PMID 23298392, 2013). "However, in women with PCOS, excess body weight and insulin resistance were associated with increased PCSK9 concentrations." (PMID 41516208, 2025). "Poor adherence to lipid-lowering therapy, low-density lipoprotein (LDL) L5 and pro-protein convertase subtilisin/kexin type 9 (PCSK9)-related lipid dysregulation, and insulin resistance may underlie this relationship." (PMID 41301929, 2025). "PCSK9 deficiency prevented statin-induced adipose insulin resistance." (PMID 36558473, 2022). "As a possible mechanism, insulin resistance, which has previously been shown to be linked with circulating PCSK9 level, could explain this finding." (PMID 35268464, 2022). "Moreover, a recent study reported that depression caused an increase in PCSK9 level, which lead to insulin resistance." (PMID 34744709, 2021). "Here, we observed that the mutation of the rs562556 polymorphism was associated with low blood glucose, which might be a result of carrying the G allele of the rs562556 polymorphism and having lower PCSK9 levels and lead to lower insulin resistance." (PMID 34075144, 2021). "The results of clinical, experimental, and genetic data indicate that PCSK9 might be influenced by several metabolic and lipid risk factors, including atherogenic lipoproteins, obesity, and insulin resistance." (PMID 35024053, 2021).
Insulin resistance (continued). "Finally, several lines of evidence including genetic studies indicate that circulating PCSK9 is directly associated with depression, a condition with higher prevalence in women and related to insulin resistance." (PMID 33776743, 2021). "Insulin resistance has been identified as a key regulator of PCSK9 expression, providing a mechanistic link between disturbances in glucose metabolism and lipid homeostasis." (PMID 41516208, 2025). "A similar study from an Italian center focuses on biomarkers found in people with insulin resistance—specifically PCSK9—and the potential effect of depression on the increase in this marker." (PMID 39518713, 2024). "The relationship between PCSK9 levels and insulin resistance parameters has been reported in previous studies in patients with and without type 2 diabetes, but information on T1D is scarce." (PMID 38532033, 2024). "One studied proprotein converts subtilisin/kexina type 9 (PCSK9), finding a relationship between this protein and atherogenic dyslipidaemia and insulin resistance." (PMID 37432258, 2023). "In this study, we found that PCSK9 plays a crucial role in statin-induced insulin resistance in adipose tissue." (PMID 36558473, 2022). "Levels of circulating PCSK9 are associated with LDL-C, as well as with insulin resistance and TG to a lesser extent." (PMID 35454343, 2022). "Putting this information together, if a fasting person has high dietary intakes of carbohydrates and fat, this results in high glucose and insulin levels (i.e., insulin resistance), increases leptin, decreases adiponectin, and increases circulating PCSK9." (PMID 35454343, 2022). "Applying a high-fructose diet, increased PCSK9 and insulin resistance were correlated, which is typically consistent with the increased HOMA-IR and insulin levels during Ramadan fasting." (PMID 35454343, 2022). "Another study showed that elevated levels of proprotein convertase subtilisin/kexin type 9 (PCSK9), a mediator of low-density lipoprotein (LDL) cholesterol, are associated with insulin resistance in depressed obese subjects." (PMID 35911274, 2022). "We found significant (p < 0.05) increases in serum levels of PCSK9, serum insulin, insulin resistance, and leptin at the end of Ramadan compared with pre-fasting levels." (PMID 35454343, 2022). "In patients with T2DM, PCSK9 expression is upregulated by insulin resistance and subsequent hyperinsulinemia." (PMID 35733117, 2022). "PCSK9, a mediator of LDL cholesterol, has been associated with a large number of cardiovascular risk factors, including insulin resistance." (PMID 35911274, 2022). "The complex relationships between PCSK9 and insulin resistance and dysregulation of adipokine secretion in relation to dietary and lifestyle modifications during Ramadan warrant further research." (PMID 35454343, 2022). "The positive correlation between PCSK9 and waist circumference, fasting glucose, insulin resistance, systolic blood pressure, diastolic blood pressure and C-reactive protein (all p < 0.01) was observed in women only." (PMID 34041285, 2021). "Several new effects of PCSK9 on diseases, such as insulin resistance and thrombus, have been revealed." (PMID 34075144, 2021). "The existence of a significant correlation between triglycerides and glucose metabolism has supported the investigation of a possible involvement of PCSK9 in glucose homeostasis and insulin resistance." (PMID 34041285, 2021). "Proprotein convertase subtilisin/kexin type 9 (PCSK9), a key regulator of low-density lipoprotein cholesterol, has been related to a large number of CV risk factors, including insulin resistance." (PMID 33143700, 2020). "A previous study found that dysbiosis of the gut microbiota exacerbates insulin resistance, possibly leading to a rise in PCSK9 expression." (PMID 33302966, 2020).